OR51A7 (olfactory receptor family 51 subfamily A member 7)
Description:
Odorant receptor.
Synonyms: OR11-27
Tractability: Antibody: UniProt places it where antibodies can reach, with medium confidence; UniProt predicts a signal peptide or a membrane-spanning region; its Gene Ontology location is reachable by antibodies, with medium confidence.
Gene: Protein-coding gene on chromosome 11 (4,903,783 to 4,909,462, forward strand). Ensembl gene ENSG00000176895.
Subcellular location: Cell membrane
Pathways (Reactome):
Sensory Perception: Expression and translocation of olfactory receptors
Gene Ontology:
Molecular function: olfactory receptor activity; G protein-coupled receptor activity; signaling receptor activity
Biological process: cellular response to lipid; detection of chemical stimulus involved in sensory perception of smell; G protein-coupled receptor signaling pathway; system process
Cellular component: plasma membrane; membrane
Genetic constraint (gnomAD): Loss-of-function variants: 2 observed, 1.91 expected, observed/expected ratio (o/e) 1.05, 90% interval 0.38 to 1.89. That is too few expected variants to judge how well the gene tolerates losing a copy. Missense variants: 407 observed, 390.84 expected, observed/expected ratio (o/e) 1.04, 90% interval 0.96 to 1.13. Synonymous variants: 143 observed, 140.54 expected, observed/expected ratio (o/e) 1.02, 90% interval 0.89 to 1.17.
Homologues: Orthologues: chimpanzee OR51A7 (98% identical), mouse Or51a7 (86% identical), rat Or51a7 (86% identical), rat Or51a7b (85% identical), pig OR51A7 (83% identical), rabbit OR51A7 (69% identical), tropical clawed frog or51ao1 (46% identical). Paralogues in human: OR51A4 (71% identical), OR51A2 (70% identical), OR51G2 (58% identical), OR51L1 (54% identical), OR51G1 (54% identical), OR51Q1 (51% identical), OR51I2 (50% identical), OR51F2 (49% identical), OR51C1 (49% identical), OR52K2 (49% identical), OR51B5 (48% identical), OR51E1 (47% identical), and 39 more.
Diseases named in the same sentence as OR51A7 in open-access papers:
OR51A7 is named in the same sentence as 1 disease in open-access papers, as found by Europe PMC text mining. Sharing a sentence is not in itself a finding about the gene and the disease.
OR51A7 shares sentences with these, for which no sentence is quoted: fibromatosis (1 paper).